RHOXF1 (Rhox homeobox family member 1)
Description:
Transcription factor maybe involved in reproductive processes. Modulates expression of target genes encoding proteins involved in processes relevant to spermatogenesis.
Synonyms: OTEX; PEPP1; GS1-421I3.4; TCONS_00017087; LINC01402
Tractability: No criterion of Open Targets' tractability assessment is met for any kind of drug.
Gene: Protein-coding gene on chromosome X (120,109,050 to 120,245,267, reverse strand). Ensembl gene ENSG00000101883.
Subcellular location: Nucleus
Subcellular location (Human Protein Atlas): Nucleoplasm; Cytosol
Gene Ontology:
Molecular function: protein binding; sequence-specific double-stranded DNA binding; DNA binding; DNA-binding transcription factor activity; DNA-binding transcription factor activity, RNA polymerase II-specific; RNA polymerase II transcription regulatory region sequence-specific DNA binding
Biological process: androgen receptor signaling pathway; positive regulation of gene expression; neuron development; regulation of DNA-templated transcription; regulation of transcription by RNA polymerase II
Cellular component: nucleoplasm; nucleus; chromatin
Homologues: Orthologues: chimpanzee RHOXF1 (97% identical), macaque RHOXF1 (86% identical), rat Rhox13 (30% identical), mouse Rhox13 (28% identical). Paralogues in human: RHOXF2B (28% identical), RHOXF2 (28% identical), PAX7 (25% identical), PAX3 (24% identical), ARX (24% identical), GSC (23% identical), PHOX2B (23% identical), PAX4 (22% identical), ALX4 (22% identical), DRGX (22% identical), SHOX2 (21% identical), GSC2 (21% identical), and 38 more.
Diseases named in the same sentence as RHOXF1 in open-access papers:
RHOXF1 is named in the same sentence as 7 diseases in open-access papers, as found by Europe PMC text mining. Sharing a sentence is not in itself a finding about the gene and the disease. The quoted sentences say what the papers report.
colorectal cancer (1 paper, 2011). A primary or metastatic malignant neoplasm that affects the colon or rectum. "We wished to confirm if RHOXF1 is expressed in human colorectal cancers, as reported by gene expression profiling." (PMID 21609483, 2011).
leukaemia (1 paper, 2022). "RHOXF1 (originally called as OTEX and hPEPP1) is a member of Rhox gene family, which is expressed in ovary, testis, epididymis, prostate and mammary gland and malignant diseases of prostate cancer, leukaemia and CRC." (PMID 34707247, 2022).
metastatic colorectal cancer (1 paper, 2011). "The closely related human gene RHOXF1 has been shown to be expressed in ES cells and adult germline stem cells, some established cancer lines and in primary metastatic colorectal cancer." (PMID 21609483, 2011).
tumor (4 papers, 2011 to 2025). "In the tumor tissues (T), RHOXF1 mRNA was also expressed in 7 out of 8 patients, ranging from 15 to 310 copies of mRNA." (PMID 21609483, 2011). "RHOXF1 (reproductive homeobox on X-chromosome F1) is predominantly expressed in the testis in healthy adults, where it is essential for male fertility, but its expression was also found in a number of tumor cell lines." (PMID 33333852, 2020). "Other TFs, such as PITX3, RHOXF1, and TBX15, are involved in developmental and organogenesis pathways, suggesting a more plastic tumor phenotype that might support survival in diverse microenvironments." (PMID 41238550, 2025).
cancer (2 papers, 2011 to 2020). A tumor composed of atypical neoplastic, often pleomorphic cells that invade other tissues. "Efforts to elucidate the functions of RHOXF1 in the biology of cancer and reproduction and to explore RHOXF1 as a potential therapeutic target should be undertaken." (PMID 21609483, 2011).
RHOXF1 also shares sentences with these, for which no sentence is quoted: esophageal squamous cell carcinoma (1 paper); prostate carcinoma (1).